RNU6-285P (RNA, U6 small nuclear 285, pseudogene)
Gene: Small nuclear RNA gene on chromosome 8 (73,018,945 to 73,019,044, reverse strand). Ensembl gene ENSG00000222488.
Homologues: Orthologues: chimpanzee U6 (99% identical), macaque U6 (86% identical), dog U6 (66% identical), guinea pig U6 (58% identical). Paralogues in human: RNU6-1209P (79% identical), RNU6-28P (79% identical), RNU6-86P (79% identical), RNU6-945P (79% identical), RNU6-38P (78% identical), RNU6-774P (78% identical), RNU6-812P (78% identical), RNU6-1005P (77% identical), RNU6-1024P (77% identical), RNU6-1145P (77% identical), RNU6-11P (77% identical), RNU6-1290P (77% identical), and 1288 more.